PCK1 (phosphoenolpyruvate carboxykinase 1)
Diseases named in the same sentence as PCK1 in open-access papers (continued):
Sharing a sentence is not in itself a finding about the gene and the disease.
cancer (continued). "Pck1, a CR upregulated Sirtuin Signaling Pathway gene, is associated with cancer cell gluconeogenesis and increased PCK1 expression is crucial for cancer growth in the absence of glucose." (PMID 34202278, 2021). "In line with these notions, there have been two reports on PCK1 and its role in cancer." (PMID 31841108, 2019). "To assess whether Pck1 modulation regulated cancer progression in a fully immunocompetent model as well, we depleted Pck1 in the murine CRC cell line CT26." (PMID 31841108, 2019). "However, further research is warranted to clarify the role of PEPCK (PCK1 or PCK2) in cancer cell metabolism." (PMID 26682254, 2015). "Therefore, whether PCK1 acts as a rate-limiting enzyme or a protein kinase in HCC needs to be clarified before it can be targeted for cancer therapy." (PMID 39578429, 2024). "Therefore, PCK1 plays a role in inhibiting cancer angiogenesis." (PMID 39578429, 2024). "Surprisingly, in recent years, PCK1 has been shown to be involved not only in metabolic regulation but also in protein kinase, proangiogenic factor, immune response enhancer, epigenetic regulator, and other processes involved in various physiological and pathological processes, especially cancer." (PMID 39578429, 2024). "Consequently, PCK1 expression can regulate the cell cycle and affect cancer progression." (PMID 39578429, 2024). "This is compatible to the Warburg effect, such that since the cancer cells heavily rely on aerobic glycolysis for survival, compensatory mechanisms may have been in place to overcome the reduction of glycolysis caused by MLK4 or PCK1 knockdown." (PMID 37407566, 2023). "Targeting PCK1/2 could be novel therapeutic strategies to inhibit human cancers." (PMID 34620839, 2021). "These target genes, including IGFBP1, WNT1, WNT10B, TGFB1, PCK1, and SLC2A3, are critical for cancer cell proliferation and metastasis." (PMID 42311859, 2026). "Mechanistically, MLK4(Mixed lineage kinase 4) regulates PCK1 expression at the transcriptional level by phosphorylating the transcription factor CREB to maintain aerobic glycolysis and promote cancer cell survival." (PMID 39578429, 2024). "More evidence for a non-enzymatic role by PCK isoforms, beyond GNG, is the recently reported protein kinase activity of PCK1 resulting in the phosphorylation of INSIG1/2 proteins and subsequent promotion of cancer cell growth." (PMID 38783087, 2024). "Numerous studies have confirmed that PCK1 is significantly downregulated in HCC and that PCK1 depletion inhibits apoptosis or induces cancer cell proliferation and metastasis." (PMID 39578429, 2024). "Hence, high levels of s-PCK1-Ab may be related to a high incidence of cancer." (PMID 37904164, 2023). "Activation of the Arp2/3 complex is regulated by multiple phospho-modification, and multiple regulator, including PCK1, PIK4, and NIK, which can phosphorylate the Arp2/3 complex, are potential targets against cancer invasion." (PMID 37026902, 2023). "To further examine the link of CREB phosphorylation and PCK1 transcription, we performed knockdown and pharmacologic inhibition of CREB in cancer cells." (PMID 37407566, 2023). "Phosphoenolpyruvate carboxykinase 1 (PCK1) can catalyze oxaloacetate (OAA) into PEP, and PCK1 overexpression boosts the adoptive transferred CD4+ and CD8+T cell cancer-killing functions." (PMID 36200045, 2022). "We compared the expression of the gluconeogenic enzymes PCK1 and G6PC with survival rates in several cancer types using the Kaplan-Meier plotter (Lánczky and Győrffy, 2021)." (PMID 36092708, 2022). "After selection by puromycin, stable cancer cells (PANC-1 and PATU-8988) bearing the PCK1 shRNA were established." (PMID 34620839, 2021).
cancer (continued). "In summary, gluconeogenesis enzymes PCK1 and PCK2 are expressed in cancers arising from diverse tissues, contrary to previous assumptions." (PMID 33540663, 2021). "The diverse functions of PCK1 and PCK2 in cancer cells, either promoting partial gluconeogenesis, regulating the TCA cycle or in moonlighting, nonclassical functions are not fully elucidated." (PMID 33540663, 2021). "The kidney is one of the most important sites of gluconeogenesis in humans, and the downregulation of key gluconeogenic enzymes, including Pck1, would deleteriously affect RCC cancer cell proliferation and survival." (PMID 33777519, 2021). "PCK1 is the rate-limiting enzyme in gluconeogenesis and Akt has notably been shown to phosphorylate PCK1 to drive non-canonical functions that upregulate lipogenesis and cancer cell proliferation." (PMID 40052110, 2025). "To validate our findings, we recruited a cohort of 21 cancer patients for histological confirmation, revealing significant mRNA upregulation of STAT3, IL6, MMP9, MMP3, TGFB1, VEGF and HIF1A, coupled with downregulation of LHPP and PCK1, PTEN and BLC2." (PMID 39468431, 2024). "Moreover, PCK1 knockdown has been shown to reduce glutamine utilization and the TCA cycle and inhibit cancer progression." (PMID 39578429, 2024). "There is growing evidence that PCK1 mediates cancer development through metabolic and nonmetabolic processes in specific cases." (PMID 39578429, 2024). "At present, many drugs targeting PCK1 for cancer treatment remain in the preclinical stage and have not entered clinical trials." (PMID 39578429, 2024). "PCK1 and PCK2 have also been reported to be critical for the growth of certain cancers." (PMID 37904164, 2023). "Among these candidate genes, S100A11 (r = −0.38, P = 6.23 × 10−14), has the highest negative correlation with PCK1 in The Cancer Genome Atlas (TCGA) database and has been reported to act as an oncogene in several tumors." (PMID 37166978, 2023). "Thus, oncogenic and nutrient-sensing pathways converge on the regulation of PCK1 and PCK2 in cancer cells, which ensures their flexible expression according to the nutritional state and metabolic demands." (PMID 33540663, 2021). "However, PCK1 was strikingly downregulated in HCC, and PCK1 depletion inhibited apoptosis or induced cancer cell proliferation and HCC growth in vivo." (PMID 34650217, 2021). "Given their central position in carbon metabolism, regulating the OAA-PEP-pyruvate node, PCK1 or PCK2 might play an important role in modulating metabolism and cell fate decisions in many different cancer types, especially in a glucose-poor microenvironment." (PMID 33540663, 2021). "This notion is further corroborated by another evidence showing that PCK2, but not PCK1, is highly expressed in different cancer cell lines." (PMID 32774674, 2020). "Similarly, the degradation of AKT mediated by mTORC2 inhibition enhances FOXO nuclear retention and glucose output via the activation of PCK1 and G6Pase and the consequent upregulation of phosphoenolpyruvate carboxykinase 2 (PEPCK) in cancer cells." (PMID 32629884, 2020). "Interestingly, some genes of the amplicon for which data are available in the human protein atlas, such as PCK1, PMEPA1, and RBM38, are expressed in the protein level at low to moderate levels in several cancers." (PMID 30275357, 2018). "Interestingly, increased expression of the PCK1, a key rate-limiting enzyme for gluconeogenesis, activates both gluconeogenesis and glycolysis in non-gluconeogenic tissue cancers." (PMID 39578429, 2024). "The phosphorylation of Akt-mediated phosphoenolpyruvate carboxykinase 1 (PCK1) at S90 can reduce its gluconeogenic activity and use GTP as a phosphate donor to phosphorylate Insig1/2 in the endoplasmic reticulum, which activates SREBP signaling for lipid synthesis in cancer." (PMID 35912181, 2022).
cancer (continued). "Thus, PCK1 or PCK2 enable cells to produce gluconeogenic/glycolytic intermediates for biosynthetic pathways that are essential for cancer cell proliferation in the absence of glucose." (PMID 33540663, 2021). "Thus, PCK1 or PCK2 enables the cells to produce glycolytic intermediates for biosynthetic pathways that are essential for cancer cell proliferation in the absence of glucose." (PMID 32777161, 2020). "The combined PCK1 and PCK2 score was significantly elevated in NSCLC metastases compared to primary cancers, while the glycolysis marker GLUT1 showed no differential expression in metastases versus primary tumors." (PMID 32777161, 2020). "Interestingly, concomitant knocking down of PCK1 and not G6PC along with mTOR pathway could overcome the inhibition of cancer cell proliferation and survival." (PMID 27551450, 2015).
infection (13 papers, 2012 to 2024). The state of being infected such as from the introduction of a foreign agent such as serum, vaccine, antigenic substance or organism. "Following infection of mice, loss of Pck1 or Fbp1 function reduced lung fungal burdens, with loss of Pck1 causing a stronger reduction than depletion of Fbp1." (PMID 32265333, 2020). "For Pck1-deficient yeasts, fungal burdens steadily declined from the inoculum, consistent with a requirement for gluconeogenesis throughout infection." (PMID 32265333, 2020). "Conversely, the infection of mouse primary hepatocytes with AdTAZ increased TAZ protein levels threefold compared with infection with control AdGFP and substantially inhibited the glucagon and Dex-induced mRNA expression of Pck1 and G6pc." (PMID 34622775, 2021). "Studies of Histoplasma yeasts isolated from macrophages 24 h after infection shows PCK1 expression is up-regulated in intracellular yeasts." (PMID 33178634, 2020). "No conclusions can be made from the absence of data, but an independent study of intramacrophage Paracoccidioides yeasts also showed up-regulation of the PCK1 gene after 9 h of infection." (PMID 33178634, 2020). "Furthermore, we measured the expression level of the pck1 with a luciferase reporter assay in the mutant and WT siblings in the absence and presence of infection." (PMID 35933481, 2022). "Consistent with the data from RNAseq, pck1 expression was significantly increased upon infection in the WT, but not in the mutant larvae." (PMID 35933481, 2022). "Infection of mouse primary hepatocytes with AdshTAZ reduced both TAZ mRNA expression and protein level and markedly increased the glucagon and dexamethasone (Dex)-induced mRNA expression of Pck1 and G6pc." (PMID 34622775, 2021). "PCK1 increased H3K9me3 levels, while targeting PHGDH by sgPHGDH or inhibitor NCT503 after AdPCK1 infection failed to enhance H3K9me3 levels." (PMID 37166978, 2023).
metabolic disease (13 papers, 2014 to 2026). A congenital disorder (due to inherited enzyme abnormality) or acquired (due to failure of a metabolically important organ) disorder resulting from an abnormal metabolic process. "Pck1 expression was downregulated in both gonadal WAT and inguinal WAT during aging, and adipocyte-specific Pck1 deficiency accelerated inflammaging and metabolic disorders." (PMID 41910356, 2026). "The icl–2, mls–2, and pck1–2 mutants, which have a metabolic disorder in the TAG to Suc pathway, displayed short etiolated seedling phenotypes." (PMID 34351899, 2021). "On the other hand, Pck1, as a key enzyme in gluconeogenesis, plays a crucial regulatory role in liver energy metabolism, and its functional disorders are closely related to various metabolic diseases." (PMID 41155555, 2025). "Dysregulation of PCK1 activity can contribute to metabolic disorders such as diabetes and may have implications for understanding glucose metabolism and metabolic diseases." (PMID 38670942, 2024). "Castration further leads to glycolipid metabolic disorders and increased expression of inflammatory cytokines by affecting the expression of HSD11B1, SGK1, PCK1, and SLC2A4 in abdominal adipose tissues and their regulatory factors." (PMID 35456474, 2022).
cardiovascular disease (3 papers, 2021 to 2024). "Unlike canonical drug-eluting stents that target mTOR or other pathways, PCK1 might be considered a potential target for cardiovascular diseases associated with vascular restenosis on the basis of its unique regulation of the STAT3/DRP1 pathway." (PMID 39262325, 2024).
degenerative diseases (2 papers, 2022 to 2025). "IF regulates lipid metabolism primarily via genes including FABP4, WNT10B, PCK1, PLIN1, LEPR, and ADIPOQ, providing energy for cold adaptation, whereas PF positively influences in vivo degenerative diseases mainly through genes such as ATP5F1A, ATP5PO, SDHB, NDUFS8, SDHA, and COX5A." (PMID 40136641, 2025).
kidney disease (2 papers, 2024 to 2025). "Pck1, a significant glycoheterotrophic enzyme found in the liver and kidney, has been linked to liver and kidney diseases." (PMID 39004726, 2024).
inherited metabolic disorders (1 paper, 2025). "Research has shown that the cytosolic level of PCK1 is significantly reduced in CRC, and high PCK1 deficiency can regulate gluconeogenesis and lead to inherited metabolic disorders." (PMID 40884151, 2025). "PCK1 is the cytosolic isoform of the enzyme, and PCK1 deficiency can regulate gluconeogenesis and lead to inherited metabolic disorders." (PMID 40884151, 2025).
PCK1 also shares sentences with these, for which no sentence is quoted: type 1 diabetic (3 papers); inflammatory bowel disease (2); lactic acidosis (2); malnutrition (2); multiple sclerosis (2); rheumatoid arthritis (2); adenocarcinoma (1); alcoholic fatty liver disease (1); B-cell lymphoma (1); bacterial infection (1); brain tumor (1); cardiomyopathy (1); cerebral infarction (1); colorectal adenocarcinoma (1); Gestational Diabetes Mellitus (1); glioblastoma (1); glucocorticoid deficiency (1); gout (1); hemorrhoid (1); Hypoinsulinemia (1); IgA nephropathy (1); infarcts (1); ischemic stroke (1); kidney cancer (1); liver failure (1); lymphoma (1); memory impairment (1); nonalcoholic steatohepatitis (1); oral cancer (1); osteoarthritis (1).
A further 11 diseases each share a sentence with PCK1 in 1 paper.